TLR4 (toll like receptor 4)
Diseases named in the same sentence as TLR4 in open-access papers (continued):
Sharing a sentence is not in itself a finding about the gene and the disease.
tumor (continued). "Our data from KEGG showed that five signaling pathways, including IL-17, HIF-1α, TLR4, NF-κB p65, and TNF signaling, may be the therapeutic pathways in the DOKD treatment of tumor development." (PMID 37239383, 2023). "TLR4 activation in the microenvironmental cells mediated anticancer effects by stimulating CD8-positive cytotoxic lymphocytes and altering the maturation state of tumor-surrounding dendritic cells." (PMID 36678520, 2022). "Moreover, the results of HE staining assays revealed that the morphological changes in mouse tumor tissues were significantly alleviated in the KGM+5-FU group, which was rescued after TLR4 overexpression." (PMID 37304412, 2022). "Tumor cells can release HMGB1 into the local microenvironment, where HMGB1 interacts with several receptors, such as toll-like receptor 2 (TLR-2), TLR-4, TLR-9, and the receptor for advanced glycation end products (RAGE), which can lead to tumor cell survival, proliferation, and angiogenesis." (PMID 34617194, 2022). "In our previous study, we found that CuB at 100 nM could induce pyroptosis in A549 cells through TLR4/NLRP3/GSDMD signaling pathways, and administration with CuB at 0.25 mg/kg, 0.5 mg/kg and 0.75 mg/kg inhibited the tumor growth in NSCLC xenograft mice model." (PMID 35183200, 2022). "PAUF can induce PC progression by acting as a tumor microenvironment (TME) modulator in a paracrine manner, e.g., it enhances the immunosuppressive function of immune cells via TLR-mediated signaling pathways (TLR2 and TLR4)." (PMID 36232715, 2022). "In addition to human HCC samples, tumor cells from a model with DEN-induced HCC mice were isolated and analyzed for expression of Tlr4 and Lin28a mRNA and let-7g miRNA level." (PMID 35955552, 2022). "The active ingredients of YFBP, such as luteolin, β-sitosterol, myristic acid, and vanillin, may exert anti-tumor effects by downregulating SMOX expression via anti-inflammatory signaling and regulation of the TLR4/NF-κB signaling pathway." (PMID 36353478, 2022). "FN mediates the release of inflammatory cytokines through Toll-like receptor 4 (TLR4) and the ECM to transport, mature, and activate immune cells, but prevents CD8+ T cells from reaching tumor cells; thereby preventing tumor cells from being destroyed by immune cells." (PMID 35303800, 2022). "After 3 weeks of injecting, TAK-242 (TLR4 inhibitor, 20 μg/mouse), PDTC (NF-κB inhibitor, 60 μg/mouse), or YC-1 (HIF-1α inhibitor, 20 μg/mouse) were injected into the subcutaneous tumor basement, and, after an hour, LPS (5 μg/mouse) was injected by the same method." (PMID 35464826, 2022). "In vivo, lipopolysaccharide (LPS) induces CXCR2+ and polymorphonuclear myeloid-derived suppressor cells (PMN-MDSC) accumulation through the production of TLR4-dependent CXCL1, controls CCA tumor cells to form an immunosuppressive microenvironment, and facilitates CCA tumor growth." (PMID 36147461, 2022). "The present study revealed that the active ingredients of YFBP, such as LUT, SIT, MYA, and VAN, might exert anti-tumor effects by downregulating SMOX expression through anti-inflammatory effects and the regulation of the TLR4/NF-κB signaling pathway." (PMID 36353478, 2022). "We also discovered an increased expression of S100A7 and low level of TLR4 in late‐stage tumors with or without DSS as compared to early‐stage tumor lesions." (PMID 33969603, 2022). "M1‐like macrophages may inhibit HCC development by changing tumor microenvironment, and M2‐like macrophages can promote HCC cell proliferation and invasion through activating TLR4/STAT3 signaling pathway." (PMID 34850589, 2022). "The CCA results indicated that tumor volume (P = 0.021), γδ T (P = 0.016), IL-17A (P = 0.044), IFN-γ (P = 0.033), and TLR4 (P = 0.01) were significant factors for the microbial community, implying that these factors are associated with the oral microbial community." (PMID 36000726, 2022).
tumor (continued). "Previously, we found that the fragment crystallizable (Fc) region of bevacizumab cooperates with the Toll-like receptor-4 (TLR4) ligand to induce M2b polarization in macrophages and secrete tumor necrosis factor-α (TNFα), which promotes immunosuppression, tumor metastasis, and angiogenesis." (PMID 36428773, 2022). "Similarly, anthracyclines and oxaliplatin can induce tumor cell death via the release of HMGB1, which is recognized by TLR4 expressed on DCs and subsequently activates MyD88, resulting in type I IFN production." (PMID 35292881, 2022). "Animal studies are now underway to find out how tumor TLR4 expression levels may impact the anti-tumor efficacy of the anti-PAUF treatment, and to explore the synergistic anti-tumor efficacy of inhibition on both TLR4/MyD88 dependent PAUF and B7-H3." (PMID 36232715, 2022). "Tumor-derived small extracellular vesicles (SEVs) induce pro-inflammatory cytokine expression and PD-L1 upregulation in M0 macrophages through IL-6/STAT3 and TLR4 signaling pathways, contributing to an immunosuppressive microenvironment." (PMID 36365103, 2022). "TLR4 deficiency, but not TLR2 deficiency, in hepatocyte-specific Pten-deficient mice suppressed tumour growth and hepatic inflammation." (PMID 35572649, 2022). "Our findings indicate a substantial negative connection between TLR4 and RNAss in all TCGA tumour types, implying that TLR4 is not involved in biological processes active in cancer stem cells." (PMID 35801728, 2022). "As the prolonged activation of TLR-4 during microorganism’s invasion increases oncogenic potential in the host via chronic activation of NF-κB and COX-2, it is likely that tumor progression could be inhibited by CAPE." (PMID 36142391, 2022). "Intriguingly, only knockout of TLR4, instead of CXCR3, could obviously decrease the MDSC mobilization at the early stage and reduce tumor progression at the late phase." (PMID 33990548, 2021). "Soluble TLR4 decoy receptors comprising the extracellular part of TLR4 did not interfere with the neutrophil tumor cytotoxicity." (PMID 34572138, 2021). "We detected intracellular TLR4 in most TLBR cell lines consistent with this pathway and that interaction of LPS via TLR4 directly activates lymphocytes to proliferate and survive as tumor cells in BIA-ALCL." (PMID 34771464, 2021). "YFP+ tumor cells expressed neither Tlr2 nor Cd14 and expressed little Tlr4, indicating that, in vivo, they are also unlikely to signal upon TLR2-TLR4 ligation." (PMID 34032639, 2021). "As TNC impacted expression of Cd274, we investigated gene expression with inhibitors as described and found that Cd274 was reduced in the tumor cells with the TLR4 inhibitor Cli95 yet not with the other inhibitors (Fig EV5F)." (PMID 33988305, 2021). "P. gingivalis LPS may stimulate host response via TLRs, like TLR4 and TLR2 that may prevent apoptosis and enhance tumor proliferation; it therefore cooperates in the protection of tumor cells and the progression of cancer." (PMID 33663382, 2021). "This is consistent with recent studies in which the stimulation of TLRs, especially TLR4, increased the expression of PD-L1 in tumor cells, independent of INF-γ." (PMID 33628591, 2021). "Hyaluronan was found to activate the TLR4/PI3K/Akt pathway, boost the production of inflammatory cytokines and increase the Mcl-1 levels in the neutrophils resulting in long-lived neutrophils that has lost the ability to kill tumor cells." (PMID 34572138, 2021). "In summary, the expression of Tlr2 and Tlr4 in the TME is important for the promotion of tumor growth, and when both of these receptors are absent, growth is compromised." (PMID 34032639, 2021). "Western blot using fresh tumor tissue from NSCLC patients also demonstrated the high level of TLR4, but not of MOR (P < 0.01)." (PMID 33628591, 2021). "RNA sequencing and TCGA dataset analyses detected that AAL may regulate the expression of JUN, TLR4, and MYD88 to suppress tumor proliferation." (PMID 34337031, 2021).
tumor (continued). "Other tumor stromal cells, such as fibroblasts and endothelial cells also respond to TLR ligands, most consistently those specific for TLR2 and TLR4, which contributes to inflammation, tissue remodeling, and angiogenesis, though studies of these functions in TME are limited." (PMID 35048056, 2021). "At the pathway level, while several genes involved in TLR signaling (TLR3, TLR4, IRAK1) co-varied positively with Methylibium and Enhydrobacter in healthy control networks, these associations were not identified in tumor networks." (PMID 33863341, 2021). "The result showed that treatment with PcrV-primed WT BMDMs, but not TLR4−/− or MyD88−/− BMDMs, decreased tumor growth and weight." (PMID 34900687, 2021). "In CT26 tumor isografts, the numbers of apoptotic cells and the activity of caspase-3, which were detected using TUNEL assay and immunofluorescence, respectively, were found significantly increased by TLR4 knockout." (PMID 34479599, 2021). "Furthermore, GSEA analysis indicated that TLR4 co-expressed genes mainly participated in immune activation, leukocyte migration, and tolerance induction, which might explain increased TILs, decreased exhaustion in the peripheral T cells, and increased exhaustion in tumor-infiltrating T cells." (PMID 34718325, 2021). "In this study, the global lipidomics and RNA sequencing data show that, in the tumor tissues of CRC-bearing mouse models, HFD not only increases tumor weight, but also the palmitic acid level and TLR4 expression, which are reduced when HFD is replaced by control diet." (PMID 34385421, 2021). "RNA sequencing dataset analyses detected that AAL may regulate the expression of JUN, TLR4, and MYD88 to suppress tumor proliferation." (PMID 34337031, 2021). "PAUF has been shown to be an endogenous ligand for TLR2 and TLR4, it activates the canonical signaling pathways of TLR2-tumor progression locus 2 (TPL2)/mitogen-activated ERK kinase (MEK)/extracellular signal-regulated kinase (ERK), but it fails to mediate TLR2-induced NF-κB activation." (PMID 34884547, 2021). "Activated TLR2 or TLR4 in OSCC can trigger the production of IL-6 and other STAT3-activating factors that then act in autocrine fashion on the OSCC receptors, which is another major cell-intrinsic pro-tumor benefit of TLR activity." (PMID 35048056, 2021). "Examples of cytokines and growth factors induced by TLR2 and/or TLR4 in OSCC cells include IL-1, IL-6, GM-CSF, TNF-alpha, CCL2, CCL20, CXCL8, and VEGF, which contribute to the inflammatory environment, vascularization, and tumor cell properties." (PMID 35048056, 2021). "In examining the dissected tumor tissues, both dipyridamole and GW4869 decreased protein contents in cyclin D1, β-catenin, YAP1, Runx2, phosphorylated Smad2/3, HMGB1, RAGE, and CD42b, except the TLR4." (PMID 33669632, 2021). "Additionally, LLC tumor-induced increase of circulating TNF-α and IL-6 was abolished in TLR4 KO mice." (PMID 34093869, 2021). "Addition of the TLR4 inhibitor peptide but not the CP7 control peptide inhibited LPS-induced TNF-α production in all BIA-ALCL tumor cells." (PMID 34771464, 2021). "As an LPS receptor, TLR4 cannot only regulate inflammatory responses but also affect noninfectious inflammatory conditions, such as tumor invasion." (PMID 33576897, 2021). "All of the TLR family members have the potential to induce dysplasia, but TLR4 has the predominant role—if there is no TLR4, the tumor does not occur." (PMID 34944856, 2021). "When cetuximab was combined with the TLR4 agonist LPS, we observed enhanced tumor cell killing when PBMCs were used as effector cells, but not when purified NK cells were used." (PMID 34681717, 2021). "Stimulation of TLR4 that can enhance the anti-tumor response and the beneficial effects of TLR4 stimulation while eliminating the negative effects remains a challenge for cancer researchers." (PMID 33669782, 2021).
tumor (continued). "The researchers claimed that activation of toll-like receptor-4 (TLR-4) conferred an antitumor effect on human BMSCs, which were named MSC1; after TLR-3 activation, however, the human BMSCs were converted to MSC2, which promoted tumor growth and metastasis." (PMID 34869325, 2021). "Lipopolysaccharide binding protein (LBP) was a key serum molecule for TLR4 internalization, which could induce IFN-β expression and involved in tumor immunotherapy response." (PMID 34177903, 2021). "Furthermore, TLR4 activated the immune response in TME by up-regulating multiple immune cells, including T cells, leading to the anti-tumor effect." (PMID 34588497, 2021). "The correlation between TLR4 activation by PSP and anti-tumour potential was studied in mice." (PMID 32466253, 2020). "Furthermore, ETBF-induced tumorigenesis was suppressed by knocking down TLR4 in the CRC xenograft mouse model, as shown by reduced tumor weight and tumor volume." (PMID 32684087, 2020). "Instead, in our experimental conditions, we found that TLR4 dysfunctional mice (C3H mice) had a similar tumor burden as wild type mice, implying that caspase-11 was not induced by the non-canonical inflammasome pathway." (PMID 33187551, 2020). "Notably, tumor cell-derived high-mobility group box 1 protein (HMGB1), which binds to toll-like receptor 4 (TLR4), has also been attributed to tumor cell-induced platelet aggregation." (PMID 32110917, 2020). "The clones in which the TLR4 knockdown was > 80% did not survive beyond passage 1, underscoring the significance of TLR4 in the growth of tumor cells." (PMID 33073533, 2020). "In our case, this might be explained by the fact that the NB-PDT treated tumor supernatants present TLR4 agonist activity, in agreement with the increase of HSP70 and HMGB1 that are TLR4 agonists themselves and can trigger IL-10 release." (PMID 32326519, 2020). "In addition, knockdown of TLR4 downregulated NFAT5, JMJD2B, and NANOG expression in the xenograft tumor tissues." (PMID 32684087, 2020). "The dying tumor cells can release HMGB1 that matured DCs through TLR-4-dependent manner." (PMID 33643911, 2020). "This was substantiated from the fact that its anti-tumour effect and increased thymus index and spleen index were evident in tumour-bearing C57BL/10J (TLR4+/+) mice but not in C57BL/10ScCr (TLR4−) mice." (PMID 32466253, 2020). "The present study does not refute this dogma, but the data suggest that TLR4 participates in other fundamental adhesion and growth mechanisms of tumor cells." (PMID 33073533, 2020). "In addition, the release of HMGB1 from dying tumor cells promotes interactions of toll-like receptor 4 (TLR-4), a pattern recognition receptor that signals through the TLR-4-MyD88 axis on DCs, that elicit potent immunostimulatory effects." (PMID 32317755, 2020). "More interestingly, among patients in the subgroups of Dukes A and B tumors (patients with no lymph node metastases), none of the patients lacking TLR4 expression in the tumor died from the disease." (PMID 32424768, 2020). "Assuming that the rapid uptake of fetuin‐A by cells is part of its growth‐promoting process, the present data suggest that TLR4 plays other functional roles in tumor cells that do not involve inflammatory responses." (PMID 33073533, 2020). "Assessing multiple biomarkers such as TLR4, MyD88 and MAD2 which give greater insight into the pathological makeup of a patient’s tumour may help to direct therapies and more suitable treatment combinations in order to improve overall outcome." (PMID 33370338, 2020). "In contrast, the expression of NKG2D in purified NK cells was slightly reduced by exosomes released from all tumor cell lines, but no further effect was observed after activation of TLR4 with LPS." (PMID 31186484, 2019). "The tumor treatment effect was absent in mice injected with the RPS3-treated DCs lacking TLR4 and pulsed with E7." (PMID 30819254, 2019).
tumor (continued). "Surprisingly, the effect of sleep fragmentation on tumor progression was maintained in mice lacking TLR4 effector molecules MyD88 or TRIF, although the effect was reduced." (PMID 31773065, 2019). "Utilizing C3H/HeJ mice that have nonfunctional TLR4 due to a double mutation, they observed that intact TLR4 is required for muscle wasting induced by engrafted SCCF-VII tumor cells." (PMID 31480237, 2019). "Additionally, tumor development was inhibited in ethanol-fed TLR-4−/− mice, which further proved that the sustained activation of TLR-4 in alcohol-fed mice induces HCC in synergy with HCV." (PMID 31060311, 2019). "Intraperitoneal administration of WT C57BL/6 mice with rhCNB resulted in a 50% reduction in LLC tumor growth, but failed to inhibit tumor growth in TLR4−/− littermates." (PMID 31218844, 2019). "In our whole population-based study, we retrieved 150 Finnish NPC cases and studied their tumour samples for TLR1, TLR2, TLR4, TLR5, TLR7, and TLR9 expressions by immunohistochemistry, and for the presence of EBV and high-risk HPVs with EBV RNA and HPV E6/E7 mRNA in situ hybridizations." (PMID 31238894, 2019). "The LPS-TLR4-MD-2 pathway elevates CXCR7 expression in SGC7901 cells, and TLR4/MD-2-mediated increases in CXCR7 levels modulate the proliferation and migration of tumor cells." (PMID 30636642, 2019). "Moreover, to understand the influence of TLR4 and TLR9 haplotypes on tumor progression, we correlated the haplotypes with early (I and II) and late (III and IV) tumor stages." (PMID 31278284, 2019). "It was observed that MIP therapy reduced tumor burden in wild-type and TLR4−/− mice but not in TLR2−/− mice." (PMID 31590685, 2019). "Our data suggest that the activation of TLR4 on tumor cells did not influence the number or size of released TEXs, instead, it increased their immunosuppressive potential." (PMID 31186484, 2019). "Based on the observation that tumor failed to induce IL-1β elevation in C3H/HeJ mice, the authors proposed that cancer induced muscle wasting through TLR4-mediated systemic inflammatory." (PMID 31480237, 2019). "Considering the linking role between TLR4 signaling and “activated” status of HC-MSC resembling MM-MSC behavior, we investigated whether TAK-242 affects pro-tumor capacity of MM-MSC in vivo." (PMID 31541083, 2019). "Further, genetic knockdown of TLR4 expression in NSCLC cells efficiently abrogated the gram-negative bacteria mediated tumor progression both in vitro and in vivo." (PMID 29568370, 2018). "Thus, TLR4- and IL-12-dependent NK and NKT cell activation by ISAg ultimately results in enhanced cytotoxicity against tumor cells." (PMID 30021579, 2018). "Also, intratumoral injection of GM-CSF secreting whole cell tumor cell vector (GVAX) formulated with the TLR4 agonist LPS showed potent induction of DC maturation and therapeutic efficacy in CDT26-tumor bearing mice." (PMID 30349530, 2018). "Interestingly, TLR4 and TLR5 protein expressions were also observed in tumor cell nuclei, as observed in the immunofluorescence preparations of the GBM cell lineages." (PMID 29912993, 2018). "Interestingly, TLR4 and TLR5 positivity were detected in the tumor cell nuclei by immunofluorescence in cell lineages and by immunohistochemistry in tumor specimens." (PMID 29912993, 2018). "Thus, we find that docetaxel increases lymphangiogenesis in tumor-bearing fat pads and this is mediated in part by VEGFC, but also by a host of other pro-lymphangiogenic cytokines likely induced by TLR4 pathway activation by taxanes." (PMID 29976154, 2018). "However, it was found in another study that stimulation of the monocytic cell line THP1 with tumor-exosomes induced TNF-α, IL-1β, and IL-6 through TLR2 and TLR4 signaling." (PMID 29867942, 2018). "LPS activate NF-κB signaling pathway via binding to the receptor TLR4, which is involved in noninfectious inflammatory diseases, such as tumor invasion and survival." (PMID 29308184, 2018).